NOC4L (nucleolar complex associated 4 homolog)
Synonyms: MGC3162; NET49; UTP19; Noc4
Tractability: Antibody: UniProt predicts a signal peptide or a membrane-spanning region. PROTAC: ubiquitination databases record sites on it; its protein half-life has been measured.
Gene: Protein-coding gene on chromosome 12 (132,144,425 to 132,152,473, forward strand). Ensembl gene ENSG00000184967.
Subcellular location: Nucleus membrane; Nucleus, nucleolus
Subcellular location (Human Protein Atlas): Nucleoli; Nucleoplasm
Pathways (Reactome):
Metabolism of RNA: Major pathway of rRNA processing in the nucleolus and cytosol; rRNA modification in the nucleus and cytosol
Gene Ontology:
Molecular function: protein binding; RNA binding
Biological process: protein localization to nucleolus; ribosomal small subunit biogenesis; maturation of SSU-rRNA; negative regulation of endocytosis; rRNA processing; T cell activation; ribosome biogenesis
Cellular component: nucleolus; nucleus; early endosome; Noc4p-Nop14p complex; nucleoplasm; small-subunit processome; nuclear membrane
Genetic constraint (gnomAD): Loss-of-function variants: 39 observed, 52.85 expected, observed/expected ratio (o/e) 0.74, 90% interval 0.57 to 0.96. The synonymous counts are far from expectation, so gnomAD's model fits this gene poorly and the ratio says little. Missense variants: 920 observed, 659.24 expected, observed/expected ratio (o/e) 1.4, 90% interval 1.32 to 1.47. Synonymous variants: 430 observed, 280.25 expected, observed/expected ratio (o/e) 1.53, 90% interval 1.42 to 1.66.
Homologues: Orthologues: chimpanzee NOC4L (99% identical), macaque NOC4L (97% identical), pig NOC4L (87% identical), guinea pig NOC4L (82% identical), dog NOC4L (81% identical), mouse Noc4l (79% identical), rat Noc4l (79% identical), tropical clawed frog noc4l (57% identical), rabbit NOC4L (56% identical), zebrafish noc4l (54% identical), Drosophila melanogaster CG2875 (27% identical), Caenorhabditis elegans T20B12.3 (25% identical).
Diseases named in the same sentence as NOC4L in open-access papers:
NOC4L is named in the same sentence as 7 diseases in open-access papers, as found by Europe PMC text mining. Sharing a sentence is not in itself a finding about the gene and the disease. The quoted sentences say what the papers report.
autoimmune disease (1 paper, 2021). A disorder resulting from loss of function or tissue destruction of an organ or multiple organs, arising from humoral or cellular immune responses of the individual to their own tissue constituents. "Specific ablation of Noc4l in Tregs resulted in a severe autoimmune disease through mediating ribosome biogenesis." (PMID 34675215, 2021).
diabetes (1 paper, 2021). "The glucose level was identified as the factor most negatively correlated to Noc4l transcripts vs. all diabetes-related clinical traits." (PMID 34675215, 2021).
microcephaly (1 paper, 2025). A congenital or acquired developmental disorder in which the circumference of the head is smaller than normal for the person's age and sex. "In this study, through generation and phenotypic characterization of a zebrafish noc4l knockout model, we identified severe developmental abnormalities including microcephaly, micrognathia, and embryonic lethality." (PMID 41358835, 2025).
Obesity (1 paper, 2021). Accumulation of substantial excess body fat. "Whether Noc4l in macrophages plays an important role in obesity-associated IR and inflammation remains undetermined." (PMID 34675215, 2021). "To address this question, we evaluated Noc4l expression in macrophages upon treatment with LPS and PA, which are related to obesity-induced inflammation and IR21–24." (PMID 34675215, 2021).
NOC4L also shares sentences with these, for which no sentence is quoted: infection (1 paper); Insulin resistance (1); schizophrenia (1).